INS (insulin)
Diseases named in the same sentence as INS in open-access papers (continued):
Sharing a sentence is not in itself a finding about the gene and the disease.
Insulin resistance (continued). "In obesity, hyperinsulinemia caused by insulin resistance leads to reduced growth hormone secretion, but IGF-I levels remain stable due to increased hepatic GH sensitivity, with suppressed IGFBP-1 levels in response to elevated insulin, which may decreasing the protection toward bladder cancer." (PMID 39723162, 2024). "We observed that, on HFD, Endo1-KO mice tended to respond more efficiently than WT mice to exogenous insulin during insulin tolerance test (ITT), suggesting a state of lower insulin resistance." (PMID 38716728, 2024). "FEPs had significantly higher baseline fasting plasma and fasting insulin levels compared to CTR, while insulin resistance was higher only at a trend-level when compared to CTR." (PMID 39085221, 2024). "Moreover, the brain's insulin resistance could reduce the sensitivity of the brain to insulin and could deteriorate the glymphatic function, leading to Aβ accumulation in the neuronal insulin signal pathway with insulin resistance." (PMID 38515515, 2024). "The vicious cycle of insulin resistance and chronic exposure to excess glucose and FFA ultimately leads to β cell damage, impairing the capacity for insulin synthesis and secretion." (PMID 40302954, 2024). "The longitudinal change in insulin and insulin resistance levels of CHR-C differed significantly from the change of CTRs (insulin: group by time t73 = 3.684, p < 0.001 and insulin resistance: group by time t73 = 3.501, p < 0.001)." (PMID 39085221, 2024). "Together, these data suggest that dysregulation of insulin- and AMPK-mediated Pink1 mRNA localization and PINK1 activity are contributing to mitochondrial dysfunction under pathological conditions modelling insulin resistance in vitro." (PMID 38504131, 2024). "Variations in insulin resistance markers (logHOMA, QUICKI, and McAuley values) were found, resulting in increased insulin sensitivity." (PMID 39796448, 2024). "Thus, the fact that subjects with obesity and type 2 diabetes who require insulin have the highest restenosis rates could be attributed to their insulin resistance and relative insulin deficiency rather than their hyperinsulinemia." (PMID 39195275, 2024). "In established T2D, insulin resistance arises in peripheral tissues, primarily in the skeletal muscle (SKM), and decreases glucose-induced insulin secretion by pancreatic β cells." (PMID 38255314, 2024). "Homeostatic model assessment for insulin resistance (HOMA-IR) values, calculated from the time 0 glucose and insulin concentrations as an indicator of insulin resistance, were significantly higher in HFD mice." (PMID 38687608, 2024). "Additionally, omega-3 PUFAs also downregulated mitochondrial fission proteins and improved insulin signaling, suggesting that the anti-obesity effects of omega-3 on insulin resistance development may be partly due to changes in mitochondrial dynamic behavior in skeletal muscle." (PMID 38976215, 2024). "Quantitative insulin-sensitivity check index (QUICKI) analysis was significantly decreased in AAV-GFP treated mice compared with WT mice, confirming insulin resistance." (PMID 39069561, 2024). "They found that the expression of SOCS1 was significantly decreased in insulin-resistant subjects, suggesting a potential role for SOCS1 in the development of insulin resistance and type 2 diabetes." (PMID 38874740, 2024). "MAPK3 is a common target for T2DM, and evidence has shown that overactivation of MAPK3 can lead to insulin sensitivity impairment, while MAPK3 knockout can undo insulin resistance." (PMID 38903985, 2024). "Additionally, Chi3l1 can markedly blunt hepatic insulin signaling as measured by reduced pAKT, pGSK-3β, and pERK levels in NAFLD, suggesting that Chi3l1 may play a role in the development of hepatic insulin resistance associated with inflammation and lipid deposition." (PMID 39769202, 2024).
Insulin resistance (continued). "Circadian rhythms synchronize various physiological functions, and their disruption can impair glucose metabolism and insulin secretion, contributing to T2DM pathogenesis through pancreatic dysfunction, fat deposition, and insulin resistance." (PMID 39062777, 2024). "Other parameters including body mass index (BMI), fasting glucose, lipid profile, and insulin were also assessed and homeostatic model assessment (HOMA) was used to estimate insulin resistance." (PMID 39100807, 2024). "Insulin sensitivity will be assessed using the Homeostatic Model Assessment for Insulin Resistance (HOMA-IR), a validated surrogate method for estimating insulin sensitivity." (PMID 39345888, 2024). "In support of this hypothesis, Tamura found impaired insulin clearance and hyperinsulinemia in apparently healthy Asian people without obesity or notable insulin resistance, suggesting that this change may be an initial trigger that drives subsequent insulin resistance." (PMID 39769002, 2024). "Even in the absence of weight reduction, this dietary approach not only diminishes liver steatosis but also enhances insulin sensitivity among individuals with MASLD and insulin resistance." (PMID 38397999, 2024). "The triglyceride-glucose (TyG) index, triglyceride to high-density lipoprotein cholesterol (TG/HDL-C) ratio and metabolic score for insulin resistance (METS-IR) have been shown to be simple and reliable non-insulin-based surrogates for IR." (PMID 38184591, 2024). "OB cats had important changes in their lipid profile, with a significant increase in triglycerides and total cholesterol, as well as changes in glucose metabolism with increased insulin and HOMA-IR index, leading to insulin resistance." (PMID 39328456, 2024). "Insulin resistance (IR) stands out as a primary contributor to PCOS, with enhancing insulin sensitivity emerging as a crucial strategy in its treatment." (PMID 39376609, 2024). "From these measurements, insulin resistance index (IRI) and QUICKI were calculated to determine the effect of H4CBD on peripheral insulin sensitivity during advanced MetS." (PMID 37899754, 2024). "Insulin resistance occurs in MNGIE syndrome, and disrupting Tymp blocks insulin signaling in cultured adipocytes, suggesting that adipocyte-related systemic metabolic dysfunction contributes to MNGI-related hepatic steatosis." (PMID 39190624, 2024). "Metabolic diseases such as T2D, insulin resistance, and adipose tissue dysfunction course with low systemic PRL levels, whereas PRL administration improves insulin sensitivity and decreases adipocyte hypertrophy in HFD-induced obese male rats." (PMID 38635745, 2024). "Glucose homeostasis was investigated by fasting blood glucose level, oral glucose tolerance test (GTT), insulin tolerance test (ITT), and basal insulin resistance (HOMA-IR)." (PMID 38884019, 2024). "Since insulin activates the PI3K/Akt/ mTOR pathway analogously to IGF-1, insulin resistance plays an important role in inhibiting the activation of the Akt/ mTOR protein synthesis signaling pathway in muscle atrophy." (PMID 38397848, 2024). "The direct implication of TNF-α in inducing insulin resistance in different tissues (skeletal and adipose) has been well documented, with TNF-α suppression leading to improved insulin sensitivity in vivo." (PMID 39458839, 2024). "SAT is characterized by more numerous small adipocytes, and it is more insulin-sensitive than VAT due to a higher expression of IRS-1, protecting it from insulin resistance." (PMID 39728000, 2024). "Alpha-tocopherol also correlated with markers of insulin resistance including HOMA-IR and serum insulin." (PMID 39195507, 2024). "We found that LPIN1 expression correlates with measures of skeletal muscle and hepatic insulin sensitivity and inversely correlates with hepatic de novo lipogenesis (DNL), a sensitive marker of hepatic insulin resistance and a characteristic of MASLD." (PMID 39405118, 2024).
Insulin resistance (continued). "HCV-induced oxidative stress, insulin resistance, and steatosis contribute to HCC development by disrupting lipid metabolism and insulin signaling pathways." (PMID 39000296, 2024). "In the manifestation of insulin resistance, protein tyrosine phosphatase 1B (PTP1B) plays a significant role as a negative regulator of insulin signaling." (PMID 39275157, 2024). "Previous studies have used traditional IR marker like homeostatic model sssessment for insulin resistance (HOMA-IR), as well as non-insulin-based IR markers like the triglyceride glucose index." (PMID 38572476, 2024). "DM covers two major mechanisms: increased blood sugar and impaired insulin signaling, either from insulinopenia (T1DM) or insulin resistance (T2DM)." (PMID 39061964, 2024). "Furthermore, it restored insulin sensitivity in insulin-resistant mice as well as mice fed an HFHFr diet; these results strongly indicate that ATRA may serve as a viable treatment option for NAFLD-associated insulin resistance." (PMID 38732128, 2024). "Measures of insulin sensitivity (i.e., glucose to insulin ratio (GIR), homeostatic model assessment for insulin resistance (HOMAIR), quantitative insulin sensitivity check index (QUICKI)) were calculated using standard equations." (PMID 38613023, 2024). "Insulin resistance develops early in T2DM, when β cell degeneration and relative insulin shortage limit glucose tolerance." (PMID 38952685, 2024). "Homeostatic model assessment of insulin resistance (HOMA-IR), single point insulin sensitivity estimator (SPISE), Matsuda index, insulinogenic index (IGI), and oral disposition index (ODI) were calculated." (PMID 38087928, 2024). "Metformin has been shown to control insulin resistance by activating AMPK, thereby increasing insulin sensitivity and peripheral glucose uptake." (PMID 38791227, 2024). "Angiotensin II impairs adipogenesis in VAT via PPARγ inhibition and promotes insulin resistance through activation of ERK1/2, which inhibits insulin phosphorylation of Akt." (PMID 39063184, 2024). "We and others have noted that insulin resistance, as seen with obesity, metabolic syndrome, PCOS, and type 2 diabetes, extends to insulin’s vascular actions." (PMID 38170166, 2024). "Here, the authors show that BMP and LGR signaling mediate communication between muscle, neuronal, and adipose tissues to enhance insulin signaling, identifying LGR as key in protecting against insulin resistance." (PMID 39033139, 2024). "In hepatic insulin resistance, the relationship between IGFBP-1 and insulin changes, with higher concentrations of insulin required to suppress IGFBP-1 secretion." (PMID 39595651, 2024). "GPNMB-ECD overexpressing mice displayed severe insulin resistance, in which treatment with GPNMB-neutralizing antibodies significantly improved metabolic parameters and insulin sensitization." (PMID 38789534, 2024). "Of the three non-responsive VUS carriers, the p.Gln175Glu carrier was of South Asian heritage and overweight with an elevated insulin requirement before switch and raised HOMA-IR, indicating insulin resistance and type 2 diabetes." (PMID 37798422, 2023). "Insulin resistance is often regarded as a strong marker of DKD and is characterized by hyperinsulinemia and reduced insulin action, affecting many classical insulin-regulated pathways in the kidney and vasculature." (PMID 36776877, 2023). "The main pathophysiological mechanisms of glucose homeostasis alterations in PPGL, related to catecholamine hypersecretion, are impaired insulin and glucagon-like peptide type 1 (GLP-1) secretion and increased insulin resistance." (PMID 36982228, 2023). "Although prolonged high-fat diet feeding resulted in obesity, our KI lineage is protected from developing insulin resistance, with increased KITT and adiponectin and decreased insulin levels." (PMID 37189379, 2023).
Insulin resistance (continued). "Insulin resistance is a hallmark of T2DM, and though less common in T1DM, can be observed during pubertal development and inter-current illness, and may also be related to obesity, sedentary lifestyle, family history of T2DM, and weight gain associated with intensive insulin therapy." (PMID 37958667, 2023). "Recently, SHP2 was found to promote inflammation-driven insulin resistance, and pharmacological SHP2 inhibition in diabetic mice specifically reduced metaflammation and suppressed macrophage activation, thereby enhancing insulin sensitivity in mice." (PMID 36843936, 2023). "In rat insulinoma (INS-1) β cells, the role of miR-126in insulin resistance comes from its effect on the protein insulin receptor substrate 1 and 2 (IRS-1/2), which are involved in hepatic glucose homeostasis and insulin signaling." (PMID 37371692, 2023). "JNK promotes insulin resistance by inhibiting the phosphorylation of insulin receptor substrate 1 (IRS-1), a key protein in the insulin signaling cascade." (PMID 37238736, 2023). "SIRT2 plays a vital role in supporting insulin resistance, and downregulation of SIRT2 improves insulin sensitivity." (PMID 36815979, 2023). "Since activation of PI3K is essential for insulin performance, PTEN is known to be effective in developing insulin resistance by reducing PI3K." (PMID 36997916, 2023). "In the absorptive phase, a larger insulin-dependent, GLUT4-mediated glucose uptake and metabolism by skeletal muscle occurs, which is decreased in insulin resistance." (PMID 38292764, 2023). "An increased amount of GLUT-4 in adipose tissue is a good marker of systemic insulin sensitivity and decreased level of IRS-1 was reported to be involved in insulin resistance." (PMID 37447192, 2023). "Lower SO-spindle coupling predicted higher (i.e., worse) next-day insulin resistance the following day, quantified using the validated metric of HOMA-IR—the marker of insulin sensitivity (r = −0.213, n = 634, p < 0.001)." (PMID 37421946, 2023). "129X1 apoA-IV−/− mice developed obesity and insulin resistance from HFD feeding, whereas C57BL/6J apoA-IV−/− mice showed average body weight and glucose intolerance from insufficient β-cell insulin secretion." (PMID 37960308, 2023). "The major forerunner of all the components of MetS is Insulin Resistance (IR) which is measured by the Homeostasis Model Assessment of Insulin Resistance (HOMA-IR) and requires the measurement of fasting plasma insulin levels." (PMID 36788883, 2023). "On the other hand, after a daily/weekly aerobic program, HOMA-IR has been found to have decreased, indicating reduced insulin resistance; blood glucose AUC in the OGTT was also lower, and insulin sensitivity measured by various methods also showed improvement." (PMID 37887399, 2023). "Due to the pathophysiological link between insulin resistance (IR) and PCOS abnormalities, insulin sensitizers have routinely been used as a treatment." (PMID 37575860, 2023). "Among them, insulin signalling is impaired in both AD and T2DM, and the definition of AD as type 3 diabetes is based on the observed insulin resistance." (PMID 36901549, 2023). "For instance, insulin resistance is seen in T2DM and polycystic ovary syndrome (PCOS), characterized by the body’s weak response to insulin and the consequential need for the pancreas to produce more insulin to maintain healthy blood glucose levels." (PMID 37937009, 2023). "To utilize this atlas of adipocyte-specific GSK3 substrates to analyze our insulin signaling data, we next mapped the 274 putative GSK3 substrate phosphosites onto our 3T3-L1 insulin resistance phosphoproteome." (PMID 36808134, 2023). "The reduction in blood glucose levels or percentage after insulin loading was significantly lower for Gls2 CKO mice than for RIP-Cre mice, showing insulin resistance." (PMID 37147373, 2023).
Insulin resistance (continued). "CRP has been shown to inhibit insulin signaling through Fcγ, and genetic elimination of CRP confers resistance to obesity and insulin resistance in rats." (PMID 37893085, 2023). "Previously, a predictive model for the development of insulin resistance in patients with PCOS was constructed using variables related to reproductive hormones, BMI, skin folds and insulin." (PMID 37854181, 2023). "In the short-term therapy of insulin resistance in PCOS, the potential use of insulin-sensitizing medications has recently been studied." (PMID 37954695, 2023). "Fasting serum insulin numerically decreased in mice treated with VSG (1.4 ± 0.3 vs. 2.2 ± 0.3 pmoL/L; p = 0.08) and homeostatic model assessment of insulin resistance (HOMA‐IR) was significantly reduced in VSG mice only." (PMID 37208943, 2023). "Insulin resistance was calculated by hemostasis model assessment of insulin resistance (HOMA-IR) and quantitative insulin sensitivity check index (QUICKI)." (PMID 37773140, 2023). "Further, insulin‐sensitive tissues will reduce glucose uptake by phosphorylating insulin receptor substrate (IRS)‐1 via serine/threonine kinase cascade, leading to insulin resistance in T2DM." (PMID 36721851, 2023). "Recent studies suggested that reduced insulin sensitivity in adipocytes is a precursor to impaired WAT function and whole-body insulin resistance." (PMID 37047308, 2023). "Empagliflozin administration in the pre-diabetic rats improved hepatic and peripheral insulin resistance mainly decreasing hepatic DAG, but also significantly reducing plasma insulin levels." (PMID 37152929, 2023). "Whole-body insulin sensitivity (ISI), insulinogenic index (IGI), oral disposition index (ODI), and insulin resistance (HOMA-IR) were estimated accordingly." (PMID 36996012, 2023). "Inhibition of AKT phospholation in POMC neurons induced age‐ and diet‐related insulin resistance, while, increasing PI3K activity, the upstream of AKT, in POMC neurons improved insulin and glycemic responses." (PMID 36042571, 2023). "Although PID1 was reported to induce insulin resistance in the transgenic mice, hepatoma cells with PID1 overexpression still retained the capacity to respond to insulin in our study." (PMID 37117198, 2023). "Nevertheless, insulin resistance abolished the effect of IGF-I on APP phosphorylation at T688, suggesting that treatment with insulin and IGF-I cannot be beneficial in AD patients with insulin resistance, metabolic syndrome, or diabetes." (PMID 38203429, 2023). "Another key actor in the development of both inflammation and insulin resistance is TLR4, which is expressed in insulin target tissues." (PMID 37371102, 2023). "Below we discuss some of the remaining barriers that limit our understanding of insulin signalling and GLUT4 traffic impairment in insulin resistance." (PMID 37248992, 2023). "Homogeneous polysaccharides from Sargassum pallidum ameliorate insulin resistance by upregulation of PI3K, Glycogen synthase (GS), and IRS-1 expression in insulin-resistant HepG2 cells." (PMID 36627919, 2023). "Further, we intended to check hyper-insulinemic insulin resistance that was responsible for the rise in FBG levels; we measured serum insulin concentration in response to antioxidant vitamins in glyphosate-exposed rats." (PMID 38274944, 2023). "Acarbose improves insulin resistance, which in turn reduces free fatty acid (FFA) levels by inhibiting peripheral lipolysis, as insulin has antilipolytic effects." (PMID 37990256, 2023). "The majority of these studies employed C-peptide-based homoeostasis model assessment indices (HOMA, or its updated variant, HOMA2, using fasting insulin and glucose), as surrogates for insulin resistance (HOMA2-IR) and insulin secretion (HOMA2-B)." (PMID 37798471, 2023). "Insulin resistance was observed in the PCOS group, whereas 1,25(OH)2D increased insulin sensitivity." (PMID 37124226, 2023).